CCN2 (cellular communication network factor 2)
Diseases named in the same sentence as CCN2 in open-access papers (continued):
Sharing a sentence is not in itself a finding about the gene and the disease.
alcohol abuse (1 paper, 2023). The use of alcoholic beverages to excess, either on individual occasions ("binge drinking") or as a regular practice. "YAP has been found activated in the liver of patients with a history of alcohol abuse, and it is also activated in the livers of chronic/binge alcohol-treated mice, associated with increased CCN2/CTGF, although whether this happens in skeletal muscle remains unknown." (PMID 36675170, 2023).
anaplastic astrocytoma (1 paper, 2024).
B-acute lymphoblastic leukemias (1 paper, 2021). "Overexpression of CCN2 is seen in the majority of B-acute lymphoblastic leukemias, especially in certain cytogenetic subgroups associated with poor outcome." (PMID 33428075, 2021).
bladder tumors (1 paper, 2017). "Compared with the normal urothelium, bladder tumors showed significantly higher expression of CCN2." (PMID 29029514, 2017).
carcinoid syndrome (1 paper, 2010). "Using cut-off values determined by ROC curve analysis, plasma CCN2 ≥ 86 μg/L, age ≥ 67 years, presence of ≥ 9 liver metastases and duration of illness ≥ 46 months were significantly associated with at least mild or greater TR/PR, as was presence of the carcinoid syndrome." (PMID 20053285, 2010).
chordoma (1 paper, 2014). Chordomas are rare malignant tumors arising from embryonic remnants of the notochord in axial skeleton. "Our study was aimed at investigating the effects of hypoxia and CCN2 on chordoma cells, using the human U-CH1 cell line." (PMID 25541962, 2014). "In this study, we sought to better understand the role of the tumour microenvironment by specifically investigating the effects of hypoxia and CCN2 on the regulation of chordoma cells using the human U-CH1 cell line." (PMID 25541962, 2014). "We demonstrate that components of the microenvironment influence the chordoma cell phenotype and that cells respond to hypoxia and exogenous CCN2 by up-regulating progenitor cell-like properties." (PMID 25541962, 2014). "Studies have demonstrated that a large volume of chordoma tumours are hypoxic and that CCN2 is a direct downstream target of T in chordoma." (PMID 25541962, 2014). "Interestingly, exposure of chordoma cells to hypoxia induced more pronounced changes in in vitro cell behaviour than did exposure of cells to CCN2." (PMID 25541962, 2014). "Overall, this study highlights the importance of multiple factors within the tumour microenvironment and how hypoxia and CCN2 may regulate human chordoma cell behaviour." (PMID 25541962, 2014). "Based on these findings, we speculate that in addition to independent CCN2 and HIF-1α induced pathways, there could be interaction between HIF-1α and CCN2 in chordoma cells, such that rCCN2 is decreasing HIF-1α activity under hypoxia but promoting HIF-1α activity under normoxia." (PMID 25541962, 2014). "The specific effects of hypoxia and CCN2 on chordoma cells are largely unknown." (PMID 25541962, 2014). "Through gene expression analysis, we detected expression of CCN1, CCN2, CCN3 and CCN5 in U-CH1 cells under basal conditions, and demonstrate increased expression of CCN3 and CCN5 by chordoma cells in hypoxia." (PMID 25541962, 2014). "The expression of the known chordoma marker brachyury (T) and the matricellular proteins CCN1 and CCN2 were first assessed in U-CH1 cells." (PMID 25541962, 2014). "The current study investigated the effects of hypoxia and the matricellular protein CCN2 on U-CH1 cells, as there is strong indication that these factors could be involved in the regulation of chordoma cell biology." (PMID 25541962, 2014).
cleft palate (1 paper, 2018). Cleft palate is a fissure type embryopathy that affects the soft and hard palate to varying degrees. "Although these studies of CCN2 KO mice alluded to a cleft palate phenotype, the mechanisms were unknown." (PMID 30029495, 2018). "Therefore, it is a likely possibility that the absence of CCN2 in the developing palate will cause dysregulation of the FGFR2b and FGFR2c signaling pathways resulting in a cleft palate phenotype similar to that observed in FGFR2b KO mice." (PMID 30029495, 2018). "Among previous reviews of palate development and cleft palate, the novelty of this review is its focus on the central role for CTGF/CCN2." (PMID 30029495, 2018).
colon adenocarcinoma (1 paper, 2025). "Our analysis uncovered a positive correlation between USP52 and YAP1 as well as its targeted genes CCN1 (CYR61) and CCN2 (CTGF) in the TCGA-Colon Adenocarcinoma (COAD) cohort." (PMID 40962058, 2025).
craniosynostosis syndromes (1 paper, 2018). "If the inhibitory effects of the CT domain of CCN2 prevail, absence of CCN2 may lead to a clefting phenotype similar to activating mutations of FGFR2c as seen in the numerous craniosynostosis syndromes." (PMID 30029495, 2018).
dwarfism (1 paper, 2013). "Our previous CCN2-transgenic mice under the control of the Col9a1 promoter show dwarfism several months after birth and smaller testes, but not so much difference in body length." (PMID 23555635, 2013).
female infertility (1 paper, 2020). Diminished or absent ability of a female to achieve conception. "CCN2 activity is essential for follicular development, ovulation, and corpus luteum formation, while its inhibition can lead to female infertility." (PMID 32455542, 2020).
muscular disease (1 paper, 2021). Myopathy is a peripheral nervous system disease consisting of any abnormal condition or disease of the muscular tissues; commonly designates a disorder involving skeletal muscle. "The roles for CCN2/CTGF in the nervous system might emerge as new therapeutic targets not only for the treatment of muscular diseases but also for treating degenerative pathologies of the central nervous system [42,]." (PMID 34435178, 2021).
myelodysplastic syndrome (1 paper, 2021). A clonal hematopoietic disorder characterized by dysplasia and ineffective hematopoiesis in one or more of the hematopoietic cell lines. "Higher mRNA levels of TGF-β and CCN2 have been demonstrated in BM of myelodysplastic syndrome (MDS) with fibrosis than in MDS without fibrosis, suggesting a role for both in its pathophysiology." (PMID 33428075, 2021).
necrosis (1 paper, 2022). The phenotypic observation that death has occurred in groups of cells or in one or more tissues due to external factors, such as infection, toxins, mechanical trauma, loss of blood supply and other injuries (e.g. corrosion or burning). "This cellular distribution is very similar to that previously observed for CCN2 and other 4-domain CCN proteins during formation of granulation tissue following myocardial necrosis and may point to a role of CCN5 in inhibiting the other 4-domain CCN proteins." (PMID 34854055, 2022).
neuroendocrine tumors (1 paper, 2010). "CCN2 may play a role in neuroendocrine tumor-related cardiac fibrosis and may serve as a marker of its earliest stages." (PMID 20053285, 2010).
papilloma (1 paper, 2020). A benign epithelial neoplasm that projects above the surrounding epithelial surface and consists of villous or arborescent outgrowths of fibrovascular stroma. "It would be particularly interesting to see if the deletion of CCN2 in HBs reduces the formation of papillomas in mice subjected to the two-stage carcinogenesis protocol." (PMID 32423907, 2020). "In papillomas, CCN2 expression could be observed in isolated epithelial or stromal cells and occasionally in cell clusters, which did not correlate to the HB-originating GFP-positive areas in consecutive sections of tumors, isolated from K19 Itga3 WT mice." (PMID 32423907, 2020). "As the expression of CCN2 in full-grown papillomas is very low and could not be correlated with HB-originating areas by histochemistry, its potential pro-tumorigenic role likely occurs during the initiation stage of DMBA/TPA–driven tumorigenesis." (PMID 32423907, 2020).
periodontal disease (1 paper, 2024). "Our analysis revealed a co-expression network comprising 216 genes, including prominent hub genes such as IL17RC, CCN2, BMP7, TPM1, and TIMP1, which are implicated in periodontal disease." (PMID 39659491, 2024). "Among the top five hub genes highlighted in this interactome are IL17RC, CCN2, BMP7, TPM1, and TIMP1, all of which have been implicated in periodontal disease in conjunction with peri-implant disease." (PMID 39659491, 2024). "The study identified 216 genes, with top hub genes like IL17RC, CCN2, BMP7, TPM1, and TIMP1 involved in periodontal disease." (PMID 39659491, 2024).
psychosis (1 paper, 2019). "Second, an analysis of plasma analytes in individuals at high risk of developing psychosis has suggested that conversion may be mediated by CCN2 (CTGF)." (PMID 31849729, 2019). "In addition to effects on psychosis risk, perturbed expression of CCN2 and/or CCN3 might impact upon mood symptoms and relevant personality traits." (PMID 31849729, 2019).
retinitis pigmentosa (1 paper, 2020). Retinitis pigmentosa (RP) is an inherited retinal dystrophy leading to progressive loss of the photoreceptors and retinal pigment epithelium and resulting in blindness usually after several decades. "In a mouse model of retinitis pigmentosa, photoreceptor degeneration coincides with reactive gliosis in Müller cells, which triggers Müller cell activation of the Hippo pathway components YAP/TEAD and subsequent upregulation of CCN2/CTGF." (PMID 32429045, 2020).
sarcopenia (1 paper, 2021). Progressive decline in muscle mass due to aging which results in decreased functional capacity of muscles. "CCN2/CTGF has also been found elevated in models of aging-related sarcopenia." (PMID 34063397, 2021).
skin squamous cell carcinoma (1 paper, 2017). A carcinoma arising from the squamous cells of the epidermis. "Finally, we observed that CCN2 and FN predominantly expressed in the dermis of normal human skin, stromal tissues of skin squamous cell carcinoma (SCC), and simultaneously induced in wounded human skin in vivo." (PMID 28267785, 2017).
small intestinal tumors (1 paper, 2010). "We showed positive immunostaining for CCN2 in tissue from both primary small intestinal tumors and liver metastases which is in agreement with previous findings, but we could not demonstrate any gross difference in the staining of tumor tissue in relation to strain or valvular pathology." (PMID 20053285, 2010).
tumor (485 papers, 2000 to 2026). "Previous studies have reported that CCN1 and CCN2 are associated with tumor growth, migration, and drug resistance." (PMID 40234387, 2025). "Increased CCN2 expression (log2 fold change = −4.10) was observed in the HCC tumor cells and is associated with TGFB-mediated fibrosis deposition." (PMID 33995488, 2021). "A univariate analysis revealed that tumor size, tumor number, vascular invasion, Id-1 and CCN2 expression were significantly associated with the post-operative OS and CCR of HCC patients." (PMID 31250351, 2019). "Overexpression of CCN2 in tumor cells has also been linked to increased tumor size and lymph node metastasis." (PMID 24637722, 2014). "CCN2 is also critically involved in several forms of cancers, although there is dispute about the role of CCN2 in tumor carcinogenesis and its association with malignancy." (PMID 24637722, 2014). "While altered expression of CCN2 has been associated with tumor survival and progression, it is unclear how or whether this predicted protein product would influence disease biology." (PMID 38287261, 2024). "Interestingly, loss of CCN2 expression in the late stages of the tumour promotes migration through a switch to N-cadherin expression and epithelial-mesenchymal transition, suggesting a role in tumour progression." (PMID 34205668, 2021). "Thus, the EV-associated CCN2/CTGF fragments, found in our study, may play a key functional role in tumor–stroma interaction." (PMID 32260433, 2020). "Signaling through the protein CCN2 (also known as CTGF) released by tumor cells can activate surrounding fibroblasts, inducing expression of the stemness marker Sox2 in them and turning them into activated CAFs." (PMID 40806546, 2025). "MiR-17-5p, part of the miR-17 ~ 92 cluster, has been shown to stimulate tumor angiogenesis by targeting anti-angiogenic proteins such as CCN2." (PMID 40155988, 2025). "Among these, cellular communication network factor 2 (CCN2) appeared to play a key role in the observed tumor-induced immune reprogramming." (PMID 41514627, 2025). "Analysis of publicly available datasets demonstrated an upregulation of CCN1 and CCN2 expression in tumor tissues and normal adjacent mucosa compared to healthy colon mucosa tissues." (PMID 38981023, 2024). "Mice with Col1a1-dependent Ccn2 ablation bearing B16F10 tumors showed impaired expression of canonical CAF markers including aSMA with reduced tumor angiogenesis." (PMID 38525245, 2024). "CCN1/Cyr61 (cysteine‐rich angiogenic inducer 61) and CCN2/CTGF (connective tissue growth factor) have been implicated in various stages of cancer progression, including tumor initiation, angiogenesis, invasion, and metastasis." (PMID 38545253, 2024). "The colocalization of CCN2/TGF-β/TGFBR1 in the membrane of S100A6+ tumor cells further confirmed the interaction pair." (PMID 39095854, 2024). "The top three downregulated genes in tumor-bearing group of female mice were Ctgf (cellular communication network factor 2, FC = 0.276, p = 0.0007), Cav2 (caveolin 2, FC = 0.305, p < 0.0014) and Tek (TEK receptor tyrosine kinase, FC = 0.32, p < 0.0021)." (PMID 37573456, 2023). "CCN2/CTGF overexpression was also found in HCC tumor cells that were surrounded by heavily fibrotic stroma." (PMID 36469291, 2023). "Coincidently, Ccn2/Ctgf has been found to mediate tumor-stroma interaction between hepatoma cells and HSC to accelerate HCC progression." (PMID 36469291, 2023). "In breast and prostate cancers, tumor cells and tumor stroma secrete CCN2, which promotes endothelial cell migration and induces tumor angiogenesis." (PMID 35042954, 2022). "Depletion of CCN2 in CAFs reduced the total volume of tumour, vascular volume, and tumour vasculogenesis in the B16F10 subcutaneous tumours." (PMID 36077754, 2022).
tumor (continued). "In our dataset, TME-derived TNF appears to interact with HCC tumor cells expressing TNFRSF1B to induce upregulation of HCC-derived CCN2 (log2 fold change = −4.10), MIP2 (log2 fold change = −6.14), and VCAM1 (log2 fold change = −2.46)." (PMID 33995488, 2021). "When we evaluated associations between CCN2 mRNA levels and prognosis, we found that high expression of CCN2 was associated with shorter OS in STAD and THCA and longer OS only in SKCM, suggesting that it acts as a tumor suppressor." (PMID 33833779, 2021). "The beneficial remodeling of the tumor stroma supports the potential value of these CCN3-derived peptides for targeting pathways regulated by CCN2 in PDAC." (PMID 32294968, 2020). "The CCN2-targeting mAb FG-3019 inhibited tumor growth and metastasis in the PANC-1 orthotopic preclinical model." (PMID 32294968, 2020). "To investigate the clinical significance of MMP3 and CCN2/CTGF gene expression, we searched the TCGA database of patient-derived tumor samples." (PMID 32260433, 2020). "An IL-8-neutralizing antibody and an anti-CCN2 neutralizing antibody which lead to reduced IL-6 production have both shown therapeutic potential in suppressing tumor progression of HCC in vitro and in vivo with a xenograft murine model." (PMID 32850829, 2020). "It has been also shown that MMP3 and CCN2/CTGF promote tumor progression through processes including rapid metastasis and tumor–stroma interactions." (PMID 32260433, 2020). "Together, these findings show that HBs contribute to skin tumorigenesis in an α3β1-dependent manner and suggest a role of HB SCs in creating a permissive environment for tumor growth through the modulation of CCN2 secretion." (PMID 32423907, 2020). "The study was conducted in the murine FC1199 tumor model, expressing CCN2 and growing both in vitro and in vivo, hence providing a good tool to study the activity and mechanisms of action of CCN2-targeting compounds." (PMID 32294968, 2020). "It has been shown that MMP3 and CCN2 (aka connective tissue growth factor (CTGF)) are often increased in tumor–stroma tissues or patients’ serum, and are thus biomarkers correlated with poor prognosis in cancer." (PMID 32260433, 2020). "In agreement, FC1199 tumor cells in vitro expressed the CCN2 protein: the protein was detectable in the cell lysate and was released in relevant amounts in the conditioned media." (PMID 32294968, 2020). "Many other significantly altered genes that play important roles in tumor progression were also identified to be closely related to CCN2 (all data were uploaded into GEO)." (PMID 31250351, 2019). "Cox regression analysis also revealed that increased CCN2 expression was significantly correlated with tumor number and tumor differentiation." (PMID 31250351, 2019). "In agreement, immunohistochemical analysis highlighted a strong expression of TIMP1, TSP2, and CCN2 proteins in the tumor stroma." (PMID 29941541, 2018). "Expression of CCN2 was assessed by immunohistochemistry (IHC) assay, in 57 pairs of tumor/non-tumor urothelial samples obtained from UBC patients." (PMID 29029514, 2017). "We also demonstrated the clinical significance of CCN2 expression, which was higher in UBC tissues and associated with advanced tumor stage and high pathologic grade." (PMID 29029514, 2017). "Compared with the control groups, inhibition of CCN2 obviously decelerated the growth of T24 xenografts and resulted in significant reduction in tumor size and weight at the termination of experiment." (PMID 29029514, 2017). "CCN2 as one of the CCN family proteins has been implicated in various biological processes including cell migration and tumor progression." (PMID 28870205, 2017). "In particular, connective tissue growth factor (CTGF, also known as CCN2) is preferentially produced by tumor cells, and elevated CTGF expression in tumor cells significantly correlates with poor clinical prognosis." (PMID 28423507, 2017).